EPOR (erythropoietin receptor)
Diseases named in the same sentence as EPOR in open-access papers (continued):
Sharing a sentence is not in itself a finding about the gene and the disease.
breast carcinoma (continued). "Moreover, we explored possible correlations with clinical variables and we found a down-regulation of miR-125b in metastatic breast cancers and a significant positive correlation between EPOR and ERBB2/HER2 levels, that are both targets of miR-125b and function as competing endogenous RNAs (ceRNAs)." (PMID 24165569, 2013). "For example, human breast cancer cell lines MCF-7 and T47D revealed similar CpG methylations in this region of EPOR gene, which is also a feature, which differentiates these cell lines from the others." (PMID 30606107, 2019). "Since EpoR are highly expressed in breast cancers, EPO coating on EPO-TAMNLC surfaces serve as the ligand in the binding of the nanoparticles to EpoR on the breast cancer cells." (PMID 31291309, 2019). "A study reported significant positive correlation between erythropoietin receptor (EPOR) and erb‐b2 receptor tyrosine kinase 2 (ERBB2) levels in breast cancer, both of which are targeted by miR‐125b and behave as ceRNA." (PMID 29603582, 2018). "In vitro studies in breast cancer cell lines have demonstrated that autocrine/paracrine production of EPO and EPOR under hypoxia contributes to cell survival and proliferation." (PMID 28430808, 2017). "Here we have investigated the effects of EPOR knockdown in two human breast cancer cell lines and in a xenotransplantation model designed to mimic EPO therapy in breast cancer patients." (PMID 28418910, 2017). "Recent research revealed that EPO/EPOR contributes to the mechanism of trastuzumab resistance in breast cancer cell line SKBR3, and EPOR downregulation can reverse the resistance to trastuzumab." (PMID 25426117, 2014). "Further, we analyzed the expression of functional EPOR and its antagonists, truncated (EPOR-T) and soluble EPOR (EPOR-S), in rHuEPO-treated MCF-7 cells and other breast cancer cell lines." (PMID 24294184, 2013). "Taken together our results show a mechanism for EPO/EPOR and ERBB2 co-regulation in breast cancer and confirm the importance of miR-125b in controlling clinically-relevant cancer features." (PMID 24165569, 2013). "We selected two breast cancer cell lines (MDA-MB-453 and MDA-MB-157) characterized by low-intermediate levels of endogenous ERBB2, moderate-high EPOR expression and low levels of endogenous miR-125b (if compared to normal breast, data not shown)." (PMID 24165569, 2013). "Since ERBB2 is frequently amplified or overexpressed in breast cancer, we used its 3′UTR as a driver for EPOR levels through miR-125b decoy." (PMID 24165569, 2013). "Such non-responsiveness to EPO has been previously observed in EPOR-expressing A549 cells as well as in some breast cancer cell lines." (PMID 36052260, 2022). "EPOR expression may be involved in tumor progression and proliferation in HER2-positive breast cancer." (PMID 25426117, 2014). "Primary tumors are not yet EPOR typed (like breast cancers are assessed for ER/PR expression) though this idea should be considered." (PMID 25426117, 2014). "The mechanism of EPO-EPOR and HER2 co-regulation in breast cancer was confirmed by miR-125b, which is downregulated in metastatic breast cancers and a significant positive correlation between EPOR and HER2 levels that are both targets of miR-125b was demonstrated." (PMID 25426117, 2014). "We confirmed EGR1, FOS and EPOR as transcription targets of the EPO-EPOR signaling loop, but could not correlate the expression of different EPOR isoforms with the invasiveness of breast cancer cell lines." (PMID 24294184, 2013). "Since EPOR and ERBB2 are both target of the tumor suppressor miR-125b, we searched for a correlation between EPOR and ERBB2 expression in an independent cohort of breast cancers." (PMID 24165569, 2013). "In our previous study 11 breast cancer lines and 20 lung cancer lines were examined with low/no EpoR detected in most cell lines." (PMID 23861852, 2013).
breast carcinoma (continued). "In conclusion, we demonstrated that the tumor-suppressive miR-125b is able to modulate erythropoietin/ erythropoietin receptor axis in breast cancer and display a negative correlation with its metastatic potential." (PMID 24165569, 2013). "The reduced levels of miR-125b in breast cancer cells suggests that both ERBB2 and EPOR could become up-regulated and actively cooperate to increase cell proliferation and reduce the apoptotic rate in cancer cells." (PMID 24165569, 2013). "Although EPO stimulation of cultured EPOR-expressing breast cancer cells did not result in increased proliferation, over activation of EPOR (receptor phosphorylation) or a consistent activation of canonical EPOR signaling pathway mediators such as JAK2, STAT3, STAT5, or AKT were observed." (PMID 34281163, 2021). "In contrast to the well-established signaling pathway activation mediated by EPO-EPOR in hematopoietic cells, EPO treatment of mammary carcinoma cells did not induce the phosphorylation of the JAK2/STAT5 axis- a critical pathway for physiologic EPOR function in hematopoietic cells." (PMID 17579721, 2007). "To test whether the EPOR-dependent effect on mitochondrial biogenesis requires iNOS, we analyzed mRNA, protein, and gDNA samples isolated from paraffin-embedded, MDA-MB-231 breast cancer xenografts that were produced and analyzed in a previous study, and that did or did not express EPOR." (PMID 36052260, 2022). "However, in mammary carcinoma cells, we did not observe any significant changes in the tyrosine phosphorylation of JAK2 in cells expressing EPOR-R129C." (PMID 17579721, 2007).
melanoma (18 papers, 2007 to 2023). A malignant, usually aggressive tumor composed of atypical, neoplastic melanocytes. "However, in erythroleukemic cells, EPO downregulates KIT expression and malignant transformation of melanocytes leads to a loss of KIT expression and upregulation of EPOR expression in melanoma cells." (PMID 35887076, 2022). "The expression of erythropoietin receptor mRNA was shown in 90.1% of 65 melanoma cell lines, and an increase in the number of copies of EPO and EPO loci was observed in 30 and 24.6% of 130 primary melanomas, respectively." (PMID 37894821, 2023). "The activation of EPOR in melanoma was thought to promote tumor progression and contributed to survival of tumor cells; inhibition of EPOR gene expression in non-small cell lung cancer (NSCLC) reduced the growth of NSCLC cells under hypoxia." (PMID 35359375, 2022). "Our in vitro studies demonstrate that B16 murine melanoma cells express EPOR, both at the protein and mRNA levels." (PMID 28415825, 2017). "In order to validate the usefulness of the well-characterized B16 murine melanoma tumor model that we had previously established in our laboratory, we first confirmed expression of EPOR by two independent methods." (PMID 28415825, 2017). "In most patients, a distinct subpopulation of melanoma cells (4–40%) expressed the erythropoietin receptor (EPO-R) and ErbB4 together with PD-1 and NGF-R/CD271." (PMID 24489649, 2014). "From studies performed with cell lines and cultured cells, several cytokine receptors, including ErbB family-members and the erythropoietin receptor (EPO-R) were reported to be expressed in melanomas." (PMID 24489649, 2014). "In melanoma cells, EpoR down-regulation resulted in diminished p-Erk in response to Epo stimulation." (PMID 23028796, 2012). "High levels of EPOR transcripts were reported in kidney tumours compared with normal kidney and in melanoma cell lines compared with normal melanocytes." (PMID 18349818, 2008). "Erythropoietin and erythropoietin receptor (Epo-R) are expressed in a number of cancers and are involved in breast, endometrial, melanoma and prostate tumorigenesis." (PMID 17437013, 2007). "Moreover, EpoR (erythropoietin receptor), also displayed in the interaction network, can promote angiogenesis, melanoma cell survival and has been reported to counteract cisplatin-induced cell death." (PMID 32098410, 2020). "In certain cancers, such as uterine, ovarian, melanoma, and stomach choriocarcinoma, inhibition of this autocrine/paracrine Epo/EpoR signaling pathway altered critical aspects of tumor biology, including inhibited proliferation and increased apoptotic cell death." (PMID 22188703, 2011). "Importantly, EPO/EPOR levels correlated well with angiogenesis and progression of patients with hepatocellular, squamous cell of the tongue and non-small cell lung carcinomas, neuroblastoma, melanoma, and gastric adenocarcinoma." (PMID 28703764, 2017). "Importantly, EPO/EPOR levels correlated well with angiogenesis and progression of patients with hepatocellular carcinoma, neuroblastoma, squamous cell carcinoma of the tongue, melanoma, and gastric adenocarcinoma." (PMID 25426117, 2014). "EPO induced angiogenesis in Matrigel plug assays, whereas neutralization of EPO secreted by melanoma cells resulted in decreased angiogenesis, which supports the role of EPO/EPOR in melanoma progression via stimulation of angiogenesis." (PMID 28703764, 2017). "Using a murine keratinocyte cell line (WT7) as a negative control we observed that cultured B16 melanoma cells express EPOR at both the mRNA and protein level." (PMID 28415825, 2017). "Indeed, EPO-induced angiogenesis in Matrigel plug assays, and neutralization of EPO secreted by melanoma cells resulted in decreased angiogenesis, which supports the role of EPO/EPOR in melanoma progression via angiogenesis stimulation." (PMID 25426117, 2014). "Tissue from a skin carcinoma and a malignant melanoma was also included with no EpoR detected." (PMID 23861852, 2013).
leukemia (16 papers, 2008 to 2025). A malignant (clonal) hematologic disorder, involving hematopoietic stem cells and characterized by the presence of primitive or atypical myeloid or lymphoid cells in the bone marrow and the blood. "Mutated JAK2, JAK2V617F, plays a key epigenetic role in leukemias involving the erythropoietin (EpoR), thrombopoietin, and granulocyte colony stimulator receptors." (PMID 31275057, 2019). "IGF2BP3 targets mRNAs encoding important factors in leukemia, like MYC, CDK6, HOXA genes, and EPOR, causing their stabilization and overexpression in leukemia cells." (PMID 40389480, 2025). "When subjected to s-μg using a rotary culture, an experiment on the UT-7/EPO leukemia cell line showed a noticeable decrease in surface localization, protein content, and mRNA expression of the erythropoietin receptor (EPOR)." (PMID 38255998, 2024). "Here we demonstrate that EPO protects DA3/EPOR leukemia cells from drug-induced cell death by promoting and maintaining senescence." (PMID 37543610, 2023). "TCFL5 has been previously shown to be upregulated in E/R+ pre-B-ALL, while GATA2 has been reported to contribute to the upregulation of erythroid genes, such as EPOR, a known marker gene in E/R+ leukemia." (PMID 33218352, 2020). "The question arises as to how EpoR activated JAKV617F then goes on to play a key role in leukemias that possess an EpoR phenotype." (PMID 31275057, 2019). "Other hematopoietic growth factor receptors, such as the receptors for Epo (EpoR) and M-CSF (M-CSFR), have been implicated in the pathogenesis of leukemia." (PMID 28498310, 2017). "RCC cell lines and primary renal tumor cells expressed EpoR higher than HK-2 cells, but much lower than the Epo-dependent UT-7 leukemia cells." (PMID 23028796, 2012). "The ETV6-RUNX1 fusion in ALL activates transcription of EPOR and it is likely to contribute a growth signal to leukemia, making this a potential target of interest." (PMID 23251904, 2012). "EPO and EPOR were found in 24 different types of malignant tumors, including leukemia." (PMID 37663284, 2023). "Previous studies have identified various genes including EPOR, TCFL5, and TERF2 to be specifically overexpressed in ETV6-RUNX1 leukemia." (PMID 33708624, 2021). "We surveyed EPO and EPOR expression in nine NSCLC cell lines with normal bronchial epithelial cells HBEC-3KT and EPO-dependent leukemia cells UT-7 included as controls." (PMID 29137269, 2017). "Strikingly, this IGH germline ALL group exhibited a high frequency of IKZF1 deletions and non-V(D)J rearrangements including CRLF2-IGH, EPOR-IGH, and EBF1-PDGFRß that can be exploited as leukemia-specific targets in clinical diagnostics of MRD." (PMID 31784504, 2019).
chronic kidney disease (13 papers, 2010 to 2024). Impairment of the renal function secondary to chronic kidney damage persisting for three or more months. "The present study explored the effects of rEPO to prevent renal fibrosis in adenine-induced chronic kidney disease (Ad-CKD) and their association with the expression of the heterodimer EPOR/βcR." (PMID 32184703, 2020). "is a continuous erythropoietin receptor activator with characteristics that permit a once-monthly schedule of administration for the maintenance treatment for chronic kidney disease (CKD) patients." (PMID 22990412, 2013). "Additionally, treatment using YGY extract significantly mitigated cognitive deficits in a chronic renal failure mice model by up-regulating the CaMKIIα/CREBBDNF and EPO/EPOR pathways in the hippocampus." (PMID 36875644, 2023). "Established treatment options for anemia of chronic kidney disease (CKD) are Erythropoietin Stimulating Agents (ESA), including erythropoietins (EPO alfa, beta), darbepoetin (DARBO α), pegylated epoietin (continuous erythropoietin receptor activator, CERA) and biosimilar epoetins." (PMID 20534124, 2010).
ischemia (13 papers, 2009 to 2022). A hypoperfusion of the BLOOD through an organ or tissue caused by a PATHOLOGIC CONSTRICTION or obstruction of its BLOOD VESSELS, or an absence of BLOOD CIRCULATION. "In gerbils, exogenous EPO administered directly to the brain was neuroprotective against brain ischemia, while infusion of soluble EpoR increased susceptibility to ischemia, and mild ischemia resulted in neural degeneration and impaired learning." (PMID 22567318, 2012). "The EPO interacts with erythropoietin receptor (EPOR) on neurons, which also has a variety of functions, especially in the protection of the brain after ischemia." (PMID 34867201, 2021). "For example, in healthy rodents, environmental enrichment, ambient heat or mild episodes of hypoxia can increase EpoR expression and furthermore protect neurons towards following injuries including severe ischemia." (PMID 29393890, 2018). "A study with EpoR conditional knock-down mice by Tsai and co-workers reported persisting Epo-mediated neuroprotection during ischemia." (PMID 29393890, 2018). "Erythropoietin and erythropoietin receptor (EPOR) expression in the CNS is significantly increased after ischemia, hypoxia, and other stress conditions, suggesting that EPO might be an endogenous neuroprotective protein." (PMID 31084604, 2019). "In our previous study regarding the mechanism through which HBSP protects the kidneys against 30 min ischemia followed by 48 h reperfusion injury, we found that the expression of heterodimer receptor βcR/EPOR, which is the receptor of HBSP, was upregulated by IR injury but downregulated by HBSP." (PMID 26655840, 2015). "Two weeks after femoral artery ligation, activation of the VEGF/VEGFR system and mobilization of EPCs were impaired in EPOR−/− rescued mice compared to wild-type mice, suggesting that EPO/EPOR regulates ischemia-induced angiogenesis through VEGF/VEGFR signaling." (PMID 35741081, 2022). "Although EPO-mediated reduction of ischemia-induced inflammation has been proposed to occur via reducing neuronal death rather than by direct effects upon EpoR-expressing inflammatory cells, it remains unknown whether or not EPO can play a direct role in regulating inflammatory cell responses." (PMID 22567318, 2012).
Obesity (13 papers, 2014 to 2025). Accumulation of substantial excess body fat. "Targeted deletion of EPOR in adipose tissue in mice increases susceptibility to obesity, decreases glucose tolerance, and increases insulin resistance." (PMID 39996752, 2025). "For example, in fat tissue, the loss of EPOR results in obesity and other metabolic syndrome phenotypes, suggesting that EPOR helps regulate energy homeostasis." (PMID 36052260, 2022). "Reduced neurogenesis in adult brain and increased susceptibility to stroke damage were observed in mice that lack EpoR in brain, and mice with targeted deletion of EpoR in white adipocytes were reported to be more susceptible to diet induced obesity." (PMID 24918289, 2014). "This review highlights examples of EPO protective activity in select non-hematopoietic tissue with emphasis on metabolic response mediated by EPOR expression in fat and brain and sex-specific regulation of fat mass and inflammation associated with diet induced obesity." (PMID 34603036, 2021). "In animal model studies, mice with EPO receptor (EPOR) expression limited to hematopoietic tissues and mice with adipocyte-specific deletion of EPOR exhibited obesity and decreased insulin sensitivity and glucose tolerance." (PMID 38696124, 2024). "With respect to adipose tissue, mice with erythroid-restricted EPOR expression show a disproportionate accumulation of fat mass that is greater in females that develop obesity and insulin resistance at a younger age compared with their male counterpart." (PMID 33330462, 2020). "Adipose tissue expresses EpoR and mice with selective EpoR knock out within adipose tissue show reduced total activity and develop obesity and insulin resistance." (PMID 29393890, 2018). "By increasing EPO levels, ROX may be used in treating obesity caused by high lipid intake, taking into account that the equilibrium between osteogenesis and adipogenesis is managed via EPO/EPOR signaling during the inflammation process caused by obesity." (PMID 41020856, 2025). "ΔEPORE mice with EPOR restricted to erythroid tissue exhibit decreased energy expenditure and total activity, an age-dependent increase in obesity, and a decrease in glucose tolerance and insulin sensitivity, suggesting that EPO signaling in non-erythroid tissue promotes a lean phenotype." (PMID 39996752, 2025). "Here, we show that male mice lacking EpoR in adipose tissue exhibit increased fat mass and susceptibility to diet-induced obesity." (PMID 39284834, 2024). "Of note, ageing EpoR-tKO mice, mostly pronounced in females, also develop severe obesity and insulin resistance, suggesting that targeting the tissue-specific EPO receptor might also be an effective therapy for diabetes." (PMID 34142210, 2021). "EPO/EPOR signaling plays a protective role in multiple organs and tissues such us adipose tissue, pancreas, heart, skeletal muscle,and nervous system and pathological condition such as obesity, diabetes, and cancer." (PMID 31915448, 2019). "The non-erythroid EPOR agonist ARA290 also improves diet-induced obesity and glucose tolerance providing evidence for EPO regulation of fat metabolism independent of EPO stimulated erythropoiesis." (PMID 39996752, 2025). "In contrast, females exhibit estrogen protection to diet induced obesity and high fat diet does not increase weight gain and glucose intolerance in female EPOR(nestinKO)." (PMID 34603036, 2021). "Moreover, optimum POMC neuron stimulation by leptin requires the presence of EPOR and ΔEPORE mice show lower POMC expression, contributing to the obesity, insulin resistance, and glucose intolerance seen in these mice." (PMID 34603036, 2021). "When the expression of the erythropoietin receptor (EPOR) is restricted to hematopoietic tissues and absent in other tissues, mice develop obesity and insulin resistance, together with a lower energy expenditure and greater white fat mass." (PMID 32752277, 2020).